PRAMEF9 (PRAME family member 9)
Description:
Substrate-recognition component of a Cul2-RING (CRL2) E3 ubiquitin-protein ligase complex, which mediates ubiquitination of target proteins, leading to their degradation. The CRL2(PRAMEF9) complex mediates ubiquitination and degradation of truncated MSRB1/SEPX1 selenoproteins produced by failed UGA/Sec decoding.
Gene: Protein-coding gene on chromosome 1 (13,171,848 to 13,179,459, forward strand). Ensembl gene ENSG00000204505.
Genetic constraint (gnomAD): Loss-of-function variants: 1 observed, 3.73 expected, observed/expected ratio (o/e) 0.27, 90% interval 0.094 to 1.24. That is too few expected variants to judge how well the gene tolerates losing a copy. Missense variants: 107 observed, 136.57 expected, observed/expected ratio (o/e) 0.78, 90% interval 0.67 to 0.92. Synonymous variants: 32 observed, 53.19 expected, observed/expected ratio (o/e) 0.6, 90% interval 0.45 to 0.81.
Homologues: Orthologues: mouse Pramel13 (45% identical), rat Pramef12 (44% identical), rat Pramef8 (43% identical), mouse Pramel12 (43% identical), mouse Pramel15 (43% identical), rat LOC120103107 (43% identical), rat Pramef5 (42% identical), mouse Pramel31 (42% identical), mouse Pramel16 (42% identical), mouse Gm13040 (42% identical), mouse Gm13043 (42% identical), mouse Gm13057 (42% identical), and 78 more. Paralogues in human: PRAMEF27 (99% identical), PRAMEF15 (97% identical), PRAMEF6 (97% identical), PRAMEF5 (96% identical), PRAMEF25 (96% identical), PRAMEF26 (96% identical), PRAMEF4 (96% identical), PRAMEF11 (95% identical), PRAMEF20 (80% identical), PRAMEF12 (62% identical), PRAMEF8 (62% identical), PRAMEF7 (61% identical), and 12 more.